NUP188 (nucleoporin 188)
Description:
Component of the nuclear pore complex (NPC), a complex required for the trafficking across the nuclear envelope (Probable). Required for proper protein transport into the nucleus.
Synonyms: hNup188; KIAA0169; SANDSTEF
Tractability: PROTAC: ubiquitination databases record sites on it; its protein half-life has been measured.
Gene: Protein-coding gene on chromosome 9 (128,947,683 to 129,007,835, forward strand). Ensembl gene ENSG00000095319.
Subcellular location: Nucleus, nuclear pore complex
Subcellular location (Human Protein Atlas): Nucleoplasm; Cytosol; Nucleoli
Pathways (Reactome):
Disease: Defective TPR may confer susceptibility towards thyroid papillary carcinoma (TPC); HCMV Early Events; HCMV Late Events; NEP/NS2 Interacts with the Cellular Export Machinery; NS1 Mediated Effects on Host Pathways; Nuclear import of Rev protein; Rev-mediated nuclear export of HIV RNA; SARS-CoV-2 activates/modulates innate and adaptive immune responses; Transport of Ribonucleoproteins into the Host Nucleus; Viral Messenger RNA Synthesis; Vpr-mediated nuclear import of PICs
Metabolism of RNA: Transport of Mature mRNA Derived from an Intronless Transcript; Transport of Mature mRNA derived from an Intron-Containing Transcript; Transport of the SLBP Dependant Mature mRNA; Transport of the SLBP independent Mature mRNA; snRNP Assembly; tRNA processing in the nucleus
Metabolism of proteins: SUMOylation of DNA damage response and repair proteins; SUMOylation of DNA replication proteins; SUMOylation of RNA binding proteins; SUMOylation of SUMOylation proteins; SUMOylation of chromatin organization proteins; SUMOylation of ubiquitinylation proteins
Metabolism: IP3 and IP4 transport between cytosol and nucleus; IP6 and IP7 transport between cytosol and nucleus; IPs transport between nucleus and cytosol; Regulation of Glucokinase by Glucokinase Regulatory Protein
Cell Cycle: Nuclear Pore Complex (NPC) Disassembly; Postmitotic nuclear pore complex (NPC) reformation
Cellular responses to stimuli: Regulation of HSF1-mediated heat shock response
Immune System: ISG15 antiviral mechanism
Gene Ontology:
Molecular function: structural constituent of nuclear pore
Biological process: protein import into nucleus; nucleocytoplasmic transport; RNA export from nucleus
Cellular component: membrane; nuclear envelope; cytosol; nuclear pore; nuclear pore inner ring
Genetic constraint (gnomAD): Loss-of-function variants: 80 observed, 178.72 expected, observed/expected ratio (o/e) 0.45, 90% interval 0.37 to 0.54. The upper end of that interval is the gene's LOEUF score, 0.54, which puts it in group 2 of 6, group 1 being the genes least tolerant of losing a copy. Missense variants: 1,666 observed, 1,961.1 expected, observed/expected ratio (o/e) 0.85, 90% interval 0.81 to 0.88. Synonymous variants: 763 observed, 760.29 expected, observed/expected ratio (o/e) 1, 90% interval 0.94 to 1.07.
Gene-disease validity (ClinGen):
ClinGen rates the evidence that NUP188 causes each of these diseases.
sandestig-stefanova syndrome (autosomal recessive): Definitive.
Homologues: Orthologues: chimpanzee NUP188 (99% identical), macaque NUP188 (99% identical), dog NUP188 (96% identical), rat Nup188 (95% identical), mouse Nup188 (95% identical), rabbit NUP188 (94% identical), guinea pig NUP188 (93% identical), pig NUP188 (89% identical), tropical clawed frog nup188 (71% identical), zebrafish nup188 (71% identical), Drosophila melanogaster Nup188 (23% identical).
Diseases named in the same sentence as NUP188 in open-access papers:
NUP188 is named in the same sentence as 35 diseases in open-access papers, as found by Europe PMC text mining. Sharing a sentence is not in itself a finding about the gene and the disease. The quoted sentences say what the papers report.
congenital heart disease (3 papers, 2019 to 2024). A heart disease that is present at birth. "For example, genetic variants of Nup205 and Nup188 were found in the patients with congenital heart disease and situs inversus totalis or heterotaxy." (PMID 39720592, 2024). "Genetic variants of Nup205 and Nup188 have been identified in patients with congenital heart disease and situs inversus totalis or heterotaxy, a prevalent human ciliopathy." (PMID 37908226, 2023). "In particular, a duplication of the inner ring component Nup188 was found in a patient with heterotaxy in which altered left-right patterning of the internal organs can lead to a severe form of congenital heart disease." (PMID 31553752, 2019).
gastric cancer (2 papers, 2022 to 2025). A primary or metastatic malignant neoplasm involving the stomach. "Existing literature has suggested that NUP188 may play an important role in gastric cancer." (PMID 40861463, 2025). "Finally, immunohistochemistry detected the NUP188 expression in gastric cancer tissues." (PMID 40861463, 2025). "The expression of NUP188 in gastric cancer (GC) was detected by immunohistochemistry." (PMID 40861463, 2025).
lung carcinoma (2 papers, 2024 to 2025). "Similarly, the UALCAN database confirmed that NUP188 protein level was overexpressed in colon cancer, clear cell renal cell carcinoma (RCC), uterine corpus endometrial carcinoma (UCEC), lung cancer, head and neck squamous cell carcinoma (HNSC), glioblastoma, and liver cancer." (PMID 40861463, 2025).
adrenocortical carcinoma (1 paper, 2025). "Furthermore, advanced pathologic stages showed higher NUP188 levels in adrenocortical carcinoma (ACC), KICH, and liver hepatocellular carcinoma (LIHC) while presented lower NUP188 levels in kidney renal papillary cell carcinoma (KIRP) and testicular germ cell tumors (TGCT)." (PMID 40861463, 2025).
colon adenocarcinoma (1 paper, 2025). "NUP188 showed a positive relationship with TMB in LUAD, colon adenocarcinoma (COAD), STAD, UCEC, rectum adenocarcinoma (READ), ACC, and KICH." (PMID 40861463, 2025).
Esophageal carcinoma (1 paper, 2025). A primary or metastatic malignant neoplasm involving the esophagus. "NUP188 presented a positive association with HRD in GBM, GBMLGG, LGG, LUAD, stomach and Esophageal carcinoma (STES), SARC, LIHC, BLCA, and ACC." (PMID 40861463, 2025).
glioblastoma multiforme (1 paper, 2025). "There were positive associations between NUP188 and Neo in glioblastoma multiforme (GBM), COAD, READ, UCEC, BLCA, and ACC." (PMID 40861463, 2025).
glioma (1 paper, 2025). A benign or malignant brain and spinal cord tumor that arises from glial cells (astrocytes, oligodendrocytes, ependymal cells). "Finally, NUP188 was positively related to LOH in glioma (GBMLGG), LGG, LAML, STES, PRAD, LIHC, PCPG, and BLCA, and negatively in CESC, KIPAN, UCEC, KIRC, THCA, and TGCT." (PMID 40861463, 2025).
lymph node metastasis (1 paper, 2025). "However, there was no connection between NUP188 and gender, age, differentiation, or lymph node metastasis (P>0.05)." (PMID 40861463, 2025).
mesothelioma (1 paper, 2025). A usually malignant and aggressive neoplasm of the mesothelium which is often associated with exposure to asbestos. "In overall survival (OS), NUP188 was a risk factor for patients with ACC, bladder urothelial carcinoma (BLCA), brain lower grade glioma (LGG), LIHC, mesothelioma (MESO), and skin cutaneous melanoma (SKCM)." (PMID 40861463, 2025).
metastatic prostate carcinoma (1 paper, 2025). A carcinoma that arises from the prostate gland and has spread to other anatomic sites. "In addition, elevated levels of other NUPs downregulated by bromoxib in TPP (i.e., NUP188, NUP210, NUP85, NUP62, and NUP214) were identified in metastatic prostate cancer, suggesting that NPC dysregulation may drive aggressive cancer phenotypes." (PMID 40137294, 2025).
prostate carcinoma (1 paper, 2025). A carcinoma that arises from epithelial cells of the prostate gland. "NUP188 also inhibited the hormone AR/ER signaling pathways in some cases, meaning that NUP188 might work as a cancer suppressor in breast and prostate cancer." (PMID 40861463, 2025).
sarcoma (1 paper, 2025). A usually aggressive malignant neoplasm of the soft tissue or bone. "In the disease-free interval (DFI), NUP188 played a risk role for patients with ACC, LGG, LIHC, MESO, sarcoma (SARC), SKCM, and uveal melanoma (UVM), but benefited the patients with KIRC and UCEC." (PMID 40861463, 2025).
viral infection (1 paper, 2022). "To test if any of the identified NUPs play a role in SV40 infection, we knocked down the individual NUPs and found that depletion of many of them impaired virus infection, with NUP188 KD displaying the strongest phenotype." (PMID 36067270, 2022). "Knockdown of Nesprin-2 leads to a decreased interaction between SV40 and NUP188, indicating that Nesprin-2 acts upstream of NUP188 during viral infection." (PMID 36067270, 2022).
cancer (6 papers, 2016 to 2025). A tumor composed of atypical neoplastic, often pleomorphic cells that invade other tissues. "The result showed that NUP188 was negatively associated with immune score in 22 cancers and only positively in 4 cancers." (PMID 40861463, 2025). "NUP188 was negatively associated with B cells in 18 cancers, with cytotoxic cells in 18 cancers, DC in 18 cancers, pDC 23 cancers, Th17 cells in 17 cancers." (PMID 40861463, 2025). "Meanwhile, NUP188 showed potential diagnostic accuracy in 15 cancers, with the area under the ROC curve greater than 0.7." (PMID 40861463, 2025). "NUP188 was dysregulated in most human cancers compared to normal tissues with great diagnostic accuracy." (PMID 40861463, 2025). "Our results demonstrated that NUP188 was negatively associated with three ESTIMATE scores in most cancer types." (PMID 40861463, 2025). "The GSCALite database showed the biological functions and pathways associated with NUP188 in 32 cancers." (PMID 40861463, 2025). "NUP188 is a component of the nuclear pore complex (NPC), regulates chromosome segregation, and NUP188 mutations are associated with a variety of inherited genetic syndromes and cancers." (PMID 38746380, 2024). "Our results demonstrated that NUP188 was negatively associated with infiltrations of B cells, cytotoxic cells, DCs, immature DC (iDC), plasmacytoid DC (pDC), and CD56bright NK cells in most cancer types." (PMID 40861463, 2025). "On the single-cell level of each cancer, NUP188 also has a dual role in biological behavior regulation." (PMID 40861463, 2025). "The study aimed to demonstrate the potential of NUP188 in cancer diagnosis, prognosis, and immunoregulation, thus affording a new insight into tumor therapy." (PMID 40861463, 2025). "The results above indicated that NUP188 had the potential to predict the prognosis of cancer patients." (PMID 40861463, 2025). "The RNAseq of the TCGA database demonstrated that NUP188 mRNA was unregulated in 14 cancers and only downregulated in kidney chromophobe (KICH) compared to normal tissues." (PMID 40861463, 2025). "This study about the role of NUP188 in pan-cancer provided the reference basis for the clinical application of NUP188-based therapy." (PMID 40861463, 2025). "The connections between NUP188, cancer status, genomic heterogeneity, and infiltrating lymphocytes were also explored." (PMID 40861463, 2025). "Therefore, NUP188 might become a novel diagnostic biomarker for human cancers." (PMID 40861463, 2025). "Genomic heterogeneity is an important index in measuring tumor characteristics, and we first explored the NUP188 alterations in pan-cancer via the cBioPortal database." (PMID 40861463, 2025). "NUP188 was localized to the nuclear, and a relatively strong positive staining was present in some samples of cancer tissues." (PMID 40861463, 2025). "The paired sample t-test further confirmed that NUP188 mRNA overexpression was found in 15 cancers except KICH." (PMID 40861463, 2025). "The TISIDB database confirmed that different immune subtypes showed different NUP188 levels in 12 cancer types." (PMID 40861463, 2025). "We found that NUP188 showed significant differences in different molecular subtypes of 10 cancer types." (PMID 40861463, 2025). "In this study, we compared the NUP188 mRNA and protein in different public databases, and confirmed that NUP188 was upregulated in most cancer types, but only downregulated in KICH." (PMID 40861463, 2025). "The TISIDB database demonstrated that different molecular subtypes showed different NUP188 expression in 10 cancer types." (PMID 40861463, 2025). "This study systematically explored the NUP188 expression in pan-cancer, and its prognostic value was analyzed comprehensively." (PMID 40861463, 2025). "Subsequently, we explore the influence of NUP188 on the functional status of cancer cell at the single-cell level through the cancerSEA database." (PMID 40861463, 2025).
cancer (continued). "High NUP188 expression was more common in GC tissues (334/410, 81.46%) than that in para-carcinoma tissues (24/98,24.49%) (χ2 = 123.381, P<0.001)." (PMID 40861463, 2025). "In addition, NUP188 showed positive connections to T helper cells in 25 cancers, to Tcm in 24 cancers, and Th2 cells in 26 cancers." (PMID 40861463, 2025). "We explored the NUP188 expression in various kinds of molecular subtypes of human cancers." (PMID 40861463, 2025). "The data from the GSCALite database demonstrated that NUP188 activated the apoptosis, cell cycle and DNA damage in a significant percentage of cancer types, indicating that NUP188 might play a different role in different cancers." (PMID 40861463, 2025). "NUP188 showed positive association with T helper cells and Th2 cells, and presented negative correlation to Th17 in most cancer types." (PMID 40861463, 2025). "NUP188 plays a potential role in pan-cancer diagnosis and prognosis and may serve as a novel biomarker for tumor immunotherapy." (PMID 40861463, 2025). "This research found that different immune subtypes of 12 cancers presented different NUP188 expressions, indicating that NUP188 may participate in TME regulation." (PMID 40861463, 2025). "Cox regression analysis was performed to evaluate the prognostic value of NUP188 in human cancers." (PMID 40861463, 2025). "Subsequently, NUP188 was confirmed to be a prognostic factor for OS in 9 cancer types." (PMID 40861463, 2025). "The inhibition influence of NUP188 on the RTK pathway might elucidate the mechanism of anticancer action in some cancer types." (PMID 40861463, 2025). "The results above indicated that NUP188 might inhibit the infiltrating immune cells in most cancer types." (PMID 40861463, 2025). "However, the expression level of NUP188 in human cancer is little known." (PMID 40861463, 2025). "The result confirmed that NUP188 activated the apoptosis, cell cycle, and DNA damage in multiple cancer types, but inhibited the signaling pathways like hormone ER and RTK in some cancers." (PMID 40861463, 2025). "Taken together, systematic analysis of NUP98-NSD1-bound proteome identified the ISWI family protein SMARCA5 (and its cancer co-dependent partners BPTF and NUP188) as stable interactors and revealed their potential functional co-operation in transcriptional regulation of stem cell differentiation." (PMID 35073946, 2022). "Nucleoporin 188 (NUP188) is a vital component of the nuclear pore complex that regulates cancer progression, but its role in diagnosis, prognosis, and immunoregulation in pan-cancer remains unclear." (PMID 40861463, 2025). "Finally, for DMRs whose associated genes had increased expression upon treatment with FQI1, we observed enrichment of GO terms for pathways in cancer (e.g. PIAS4, SMAD3, TRAF4, MAP2K1) and RNA transport (e.g. NUP188, EIF3A, NUP35, RAN) in both hyper and hypomethylated DMRs." (PMID 27845898, 2016).
infection (1 paper, 2022). The state of being infected such as from the introduction of a foreign agent such as serum, vaccine, antigenic substance or organism. "We found that immunoprecipitation of endogenous NUP188 does in fact pull down SV40 during infection." (PMID 36067270, 2022).
tumor (1 paper, 2025). "In vivo experiment demonstrated that NUP188 knockdown inhibited the tumor growth in subcutaneous xenograft tumor model." (PMID 40861463, 2025). "We inhibited the NUP188 expression in GC cells, and found that NUP188 knockdown in GC cells significantly impaired the tumor lethality, including cell proliferation, migration and invasion." (PMID 40861463, 2025). "In conclusion, NUP188 was overexpressed in multiple cancers, and may play a vital role in tumor diagnosis and prognosis." (PMID 40861463, 2025). "In addition, NUP188 also exhibited positive connection to central memory T cells (Tcm) which could recognize and kill tumor cells." (PMID 40861463, 2025).
NUP188 also shares sentences with these, for which no sentence is quoted: melanoma (2 papers); Situs inversus totalis (2); amyotrophic lateral sclerosis (1); Anxiety (1); ciliopathy (1); clear cell renal cell carcinoma (1); colon cancer (1); depression (1); escherichia coli infection (1); head and neck squamous cell carcinoma (1); liver cancer (1); neurodegenerative disease (1); rectum adenocarcinoma (1); Salmonella Infections (1); skin cutaneous melanoma (1); testicular germ cell tumor (1); uterine corpus endometrial carcinoma (1); uveal melanoma (1).